CNKSR3 (CNKSR family member 3)
Description:
Involved in transepithelial sodium transport. Regulates aldosterone-induced and epithelial sodium channel (ENaC)-mediated sodium transport through regulation of ENaC cell surface expression. Acts as a scaffold protein coordinating the assembly of an ENaC-regulatory complex (ERC).
Synonyms: CNK3; MAGI1; FLJ31349; CNK3/IPCEF1
Tractability: Antibody: UniProt places it where antibodies can reach, with high confidence; its Gene Ontology location is reachable by antibodies, with medium confidence. PROTAC: ubiquitination databases record sites on it.
Gene: Protein-coding gene on chromosome 6 (154,387,515 to 154,510,685, reverse strand). Ensembl gene ENSG00000153721.
Subcellular location: Cytoplasm; Apical cell membrane
Subcellular location (Human Protein Atlas): Cytosol; Mitochondria
Gene Ontology:
Molecular function: protein binding; protein-macromolecule adaptor activity
Biological process: enzyme-linked receptor protein signaling pathway; negative regulation of ERK1 and ERK2 cascade; negative regulation of peptidyl-serine phosphorylation; positive regulation of sodium ion transport; regulation of signal transduction
Cellular component: apical plasma membrane; cytoplasm; cytosol; membrane
Genetic constraint (gnomAD): Loss-of-function variants: 25 observed, 52.06 expected, observed/expected ratio (o/e) 0.48, 90% interval 0.35 to 0.67. The upper end of that interval is the gene's LOEUF score, 0.67, which puts it in group 2 of 6, group 1 being the genes least tolerant of losing a copy. Missense variants: 571 observed, 625.84 expected, observed/expected ratio (o/e) 0.91, 90% interval 0.85 to 0.98. Synonymous variants: 245 observed, 253.91 expected, observed/expected ratio (o/e) 0.96, 90% interval 0.87 to 1.07.
Homologues: Orthologues: chimpanzee CNKSR3 (99% identical), macaque CNKSR3 (98% identical), pig CNKSR3 (94% identical), rabbit CNKSR3 (94% identical), dog CNKSR3 (94% identical), rat Cnksr3 (92% identical), mouse Cnksr3 (92% identical), guinea pig CNKSR3 (92% identical), Drosophila melanogaster cnk (30% identical), Caenorhabditis elegans cnk-1 (23% identical). Paralogues in human: CNKSR2 (56% identical), CNKSR1 (25% identical), IPCEF1 (12% identical), SAMD3 (10% identical).
Diseases named in the same sentence as CNKSR3 in open-access papers:
CNKSR3 is named in the same sentence as 9 diseases in open-access papers, as found by Europe PMC text mining. Sharing a sentence is not in itself a finding about the gene and the disease. The quoted sentences say what the papers report.
asthma (1 paper, 2015). "Whereas, the second study showed two genes – CNKSR3 and SPTBN2 which expression in PBMCs differentiates between AIA and ATA, but neither CNKSR3 nor SPTBN2 has described relationship with asthma and aspirin." (PMID 26646719, 2015).
kidney disease (1 paper, 2024). "CNKSR3, a gene highly expressed in renal collecting ducts, regulates sodium transport and is upregulated by aldosterone, is targeted in protecting kidney disease progression in T2D representing a candidate gene for further investigation in the context of T2D pathogenesis." (PMID 39072272, 2024).
CNKSR3 also shares sentences with these, for which no sentence is quoted: cancer (2 papers); breast adenocarcinoma (1); diabetic retinopathy (1); glioblastoma (1); lung adenocarcinoma (1); melanoma (1); osteosarcoma (1).